COQ8A (coenzyme Q8A)
Description:
Atypical kinase involved in the biosynthesis of coenzyme Q, also named ubiquinone, an essential lipid-soluble electron transporter for aerobic cellular respiration. Its substrate specificity is still unclear: may act as a protein kinase that mediates phosphorylation of COQ3 (By similarity). According to other reports, acts as a small molecule kinase, possibly a lipid kinase that phosphorylates a prenyl lipid in the ubiquinone biosynthesis pathway, as suggested by its ability to bind coenzyme Q lipid intermediates. However, the small molecule kinase activity was not confirmed by another publication (By similarity). Shows an unusual selectivity for binding ADP over ATP.
Synonyms: ADCK3; CABC1; COQ8; SCAR9; ARCA2; COQ10D4
Tractability: Small molecule: a structure with a bound ligand is known; a high-quality ligand is known; it belongs to a druggable protein family. Antibody: UniProt predicts a signal peptide or a membrane-spanning region. PROTAC: it is named in the literature on targeted protein degradation; ubiquitination databases record sites on it; a small molecule that binds it is known.
Target class: Enzyme; Protein Kinase; Atypical protein kinase group; Kinase
Gene: Protein-coding gene on chromosome 1 (226,938,143 to 226,987,569, forward strand). Ensembl gene ENSG00000163050.
Subcellular location: Mitochondrion membrane
Subcellular location (Human Protein Atlas): Mitochondria
Pathways (Reactome):
Metabolism: Ubiquinol biosynthesis
Gene Ontology:
Molecular function: ADP binding; kinase activity; protein binding; protein kinase activity; enzyme activator activity
Biological process: phosphorylation; protein phosphorylation; ubiquinone biosynthetic process
Cellular component: mitochondrial membrane; mitochondrion; extrinsic component of mitochondrial inner membrane
Genetic constraint (gnomAD): Loss-of-function variants: 53 observed, 66.71 expected, observed/expected ratio (o/e) 0.79, 90% interval 0.64 to 1. The upper end of that interval is the gene's LOEUF score, 1, which puts it in group 4 of 6, group 1 being the genes least tolerant of losing a copy. Missense variants: 940 observed, 898.79 expected, observed/expected ratio (o/e) 1.05, 90% interval 0.99 to 1.1. Synonymous variants: 371 observed, 360.1 expected, observed/expected ratio (o/e) 1.03, 90% interval 0.95 to 1.12.
Homologues: Orthologues: chimpanzee COQ8A (99% identical), macaque COQ8A (98% identical), rabbit COQ8A (88% identical), rat Coq8a (87% identical), guinea pig COQ8A (87% identical), dog COQ8A (87% identical), mouse Coq8a (87% identical), pig COQ8A (87% identical), tropical clawed frog coq8a (68% identical), zebrafish coq8aa (66% identical), zebrafish coq8ab (57% identical). Paralogues in human: COQ8B (45% identical), ADCK5 (17% identical), ADCK1 (16% identical), ADCK2 (13% identical).
Diseases named in the same sentence as COQ8A in open-access papers:
COQ8A is named in the same sentence as 49 diseases in open-access papers, as found by Europe PMC text mining. Sharing a sentence is not in itself a finding about the gene and the disease. The quoted sentences say what the papers report.
Ataxia (32 papers, 2010 to 2025). Ataxia refers to impaired coordination of voluntary muscle movement. "Here we present a new case of primary CoQ10 deficiency due to compound heterozygous COQ8A mutations, in which the patient suffered truncal myoclonic movements, mild dysarthria and ataxia." (PMID 41568333, 2025). "COQ8A deficiency, also referred to as COQ10D4 or ADCK3-related ataxia, classically presents with childhood-onset cerebellar ataxia, seizures, and variable multisystem involvement." (PMID 41568333, 2025). "COQ8A-associated ataxia is also known as autosomal recessive cerebellar ataxia 2 (ARCA2) or autosomal recessive spinocerebellar ataxia (SCAR9)." (PMID 38722242, 2024). "In the largest multicenter study describing the clinico-genetic features of COQ8A-ataxia, missense variants were found to be predominantly grouped around the active site of the COQ8A protein (protein kinase-like superfamily domains)." (PMID 38673663, 2024). "The high sensitivity of Purkinje neurons to Coq8a mutation is further corroborated by the finding that deletion of COQ8A in Purkinje cells was sufficient to cause ataxia in a conditional mouse model." (PMID 38722242, 2024). "Recently, a Purkinje-specific conditional COQ8A knockout mouse has been generated, demonstrating the causative role of Purkinje degeneration in PCoQD-related ataxia." (PMID 38673663, 2024). "The most frequent genetic causes of PCoQD-related cerebellar ataxia are pathogenic variants in COQ8A (autosomal-recessive cerebellar ataxia type 2 -ARCA2- or SCAR9, OMIM code: 612016)." (PMID 38673663, 2024). "Of particular importance is to note that cerebellar ataxia is a typical symptom of human patients harboring mutations in COQ8A, which is well recapitulated in these mouse models." (PMID 38722242, 2024). "In mouse models of COQ8A-ataxia, pathogenic variants lead to progressive cerebellar ataxia associated with the dysfunction of Purkinje cells." (PMID 36295857, 2022). "The studied variant of the COQ8A gene has been described in patients with ubiquinone deficiency (primary CoQ10 deficiency) with cerebellar ataxia." (PMID 36295857, 2022). "Mutations in COQ8A in humans result in CoQ10 deficiency, the clinical features of which include early-onset cerebellar ataxia, seizures and intellectual disability." (PMID 35139868, 2022). "The identification of T2 hyperintensities of the dentate nuclei and the dorsal pons present novel recurrent imaging features of COQ8A‐ataxia, possibly indicating underlying metabolic changes related to COQ8A‐dysfunction." (PMID 32337771, 2020). "Here, we provide clinical, laboratory, and genetic findings of a patient with cerebellar ataxia caused by compound heterozygous mutations in COQ8A gene." (PMID 32743982, 2020). "We report the biochemical, histochemical and molecular genetic findings relating to two young, female patients, both of whom presented with early onset cerebellar ataxia and were found to harbor recessive pathogenic variants in COQ8A." (PMID 32685350, 2020). "Here, we report the clinical, biochemical, and genetic investigation of a patient from a non‐consanguineous family with an autosomal recessive cerebellar ataxia due to novel compound heterozygous mutations in the COQ8A gene." (PMID 32743982, 2020). "Subject 2 presented with characteristic features of recessive COQ8A defects, namely cerebellar ataxia and mild cognitive impairment, but identifying the causative genetic defect was challenging." (PMID 32685350, 2020). "Furthermore, under the treatable ataxias subheading, three patients were found to have variants in the COQ8A gene, which is associated with Coenzyme Q10 deficiency, a condition that can be responsive to treatment with CoQ10 supplementation." (PMID 38570878, 2024). "COQ8A‐ataxia (also known as ADCK3 or autosomal recessive cerebellar ataxia type 2 [ARCA2]) is the most common autosomal recessive cerebellar ataxia related to primary CoQ10 deficiency." (PMID 40464291, 2025).
Ataxia (continued). "Constitutive COQ8A knockout (Coq8a−/−) mice develop a mild phenotype characterized by progressive ataxia, seizures, and exercise intolerance driven by complex Q instability and coenzyme Q10 deficiency." (PMID 38673663, 2024). "COQ8A-ataxia is inherited in an autosomal recessive manner, and the first case was reported in 2008." (PMID 38673663, 2024). "It should be noted, however, that, because of the known high prevalence of ataxia in COQ8A/ADCK3 patients, individuals with unexplained ataxia are more likely to be tested for mutations in COQ8A than in other COQ genes." (PMID 38722242, 2024). "COQ8A-ataxia is a mitochondrial disease in which a defect in coenzyme Q10 synthesis leads to dysfunction of the respiratory chain." (PMID 36295857, 2022). "Mutations in COQ8A in humans result in CoQ10 deficiency (OMIM: 612,016), the clinical features of which include early-onset cerebellar ataxia, seizures and intellectual disability." (PMID 35139868, 2022). "By WES we identified compound heterozygous mutations of the COQ8A gene in a Chinese ARCA family, and we excluded common causes of ataxia." (PMID 32743982, 2020). "Mutations in COQ8A and COQ8B (previously known as ADCK3 and ADCK4) have been shown to induce a decrease of CoQ in the cerebellum and kidney causing cerebellar ataxia and nephrotic syndrome, respectively." (PMID 31480808, 2019). "Moreover, the spectrum of symptoms of encephalopathy, intellectual disability, seizures, and muscle involvement has been described in patients with variants responsible for other primary coenzyme Q10 deficiency (COQ2, COQ4, COQ6, COQ7, COQ9) as well as in patients with COQ8A-ataxia." (PMID 36295857, 2022). "In addition, a growing number of genes initially linked to other neurological phenotypes, such as developmental delay, epilepsy, or ataxia, are now recognized to cause prominent dystonia, occasionally in an isolated fashion (e.g., GNAO1, GNB1, SCN8A, RHOBTB2, and COQ8A)." (PMID 36705216, 2022). "Ataxia is not observed in patients with COQ8B mutations, but the dominant clinical feature associated with COQ8A/ADCK3 mutations is progressive cerebellar ataxia, variably combined with muscular and other neurological symptoms." (PMID 38722242, 2024). "In addition to cerebellar ataxia, subject 1 presented with a number of additional features including hip dysplasia, macrocephaly, dentinogenesis imperfecta, hypertelorism, and exophthalmos; these dysmorphic features are not consistent with previous COQ8A‐deficient phenotypes." (PMID 32685350, 2020).
coenzyme Q10 deficiency (8 papers, 2014 to 2024). A genetically heterogeneous condition, typically inherited in an autosomal recessive fashion, characterized by coenzyme Q10 deficiency. "Mutations in the COQ8A gene (also known as CABC1 or ADCK3) represent the most common form of primary coenzyme Q10 deficiency." (PMID 39850733, 2024). "Coenzyme Q10 deficiency can result from pathogenic variants in the COQ2, COQ4, COQ6, COQ8A, or COQ8B gene." (PMID 38570878, 2024). "Primary CoQ10 deficiency‐4 (COQ10D4) is the most frequent form of primary CoQ10 deficiency and caused by mutations of COQ8A (OMIM*606980) gene (also known as ADCK3 or CABC1)." (PMID 32743982, 2020). "It should be pointed out that COQ8A acts as a kinase that phosphorylates other COQ proteins and stabilizes the Q protein complex; it is not directly related to 4-HBA and other substrates, which differentiates this mechanism of action from other models of CoQ10 deficiency." (PMID 36295857, 2022).
autosomal recessive cerebellar ataxia type 2 (3 papers, 2023 to 2025). "Disease-causing variants in COQ8A were first described in 2008 (primary coenzyme Q10 deficiency-4; COQ10D4; OMIM #612016)." (PMID 36978966, 2023).
Stroke (3 papers, 2013 to 2023). Sudden impairment of blood flow to a part of the brain due to occlusion or rupture of an artery to the brain. "Stroke-like episodes were reported as a potential disease feature of several CoQ10 biosynthesis defects (COQ2, COQ4 and COQ8A)." (PMID 36978966, 2023).
astrocytomas (1 paper, 2022). "Taken together, we have demonstrated that lower CoQ10 levels and protein levels of COQ3, COQ5, COQ6, COQ7, COQ8A, and COQ9 were associated with higher tumor grades and lower CS activity or COX II level in human astrocytomas." (PMID 35204836, 2022). "The levels of COQ3, COQ5, COQ6, COQ7, COQ8A, and COQ9, but not of COQ4, were lower in Grade IV astrocytoma tissues than in controls or low-grade (Grades I and II) astrocytomas, but PDSS2 levels were higher in astrocytoma tissues than in controls." (PMID 35204836, 2022).
optic atrophy (1 paper, 2020). A disorder characterized by loss of optic nerve fibers. "This corresponds with the atypical clinical phenotype of the patient carrying this variant in a homozygous state (P51): the phenotype included—in contrast to all 59 patients with likely pathogenic COQ8A variants—optic atrophy and predominant sensory ataxia." (PMID 32337771, 2020).
paroxysmal dyskinesia (1 paper, 2025). Paroxysmal dyskinesia (PD) is a rare heterogenous group of movement disorders manifesting as abnormal involuntary movements that recur episodically and last only a brief time. "Here, we provide a rare phenotype of paroxysmal dyskinesias caused by compound heterozygous variants of COQ8A gene." (PMID 41568333, 2025). "In this case, we report paroxysmal dyskinesias and mild coordination difficulties in the limbs with an adult onset caused by compound heterozygous variants of the COQ8A gene." (PMID 41568333, 2025).
tumor (5 papers, 2017 to 2025). "Transmembrane protein 108 (TMEM108), C3orf47 and coenzyme Q8A (CABC1) were the top three genes positively correlated with tumor grade, whereas ladinin 1 (LAD1), TIAF1 and FGF11 were the top three genes negatively correlated with the tumor grade of ESCC patients." (PMID 28904855, 2017).
COQ8A also shares sentences with these, for which no sentence is quoted: cerebellar ataxia (16 papers); Cerebellar atrophy (6); mitochondrial disease (4); nephrotic syndrome (4); autosomal recessive cerebellar ataxia (3); Dystonia (3); epilepsy (3); Intellectual disability (3); neurologic disease (3); cancer (2); Cognitive impairment (2); depression (2); Encephalopathy (2); endometrial carcinoma (2); hepatocellular carcinoma (2); Seizure (2); Atrophy (1); axonal neuropathy (1); Brain atrophy (1); breast carcinoma (1); cardiac diseases (1); Childhood onset (1); cognitive decline (1); dentinogenesis imperfecta (1); developmental delay (1); Gait ataxia (1); hereditary ataxia (1); Hip dysplasia (1); homocystinuria (1); infection (1).
A further 11 diseases each share a sentence with COQ8A in 1 paper.